PPARG (peroxisome proliferator activated receptor gamma)
Diseases named in the same sentence as PPARG in open-access papers (continued):
Sharing a sentence is not in itself a finding about the gene and the disease.
pulmonary fibrosis (68 papers, 2009 to 2026). Chronic progressive interstitial lung disorder characterized by the replacement of the lung tissue by connective tissue, leading to progressive dyspnea, respiratory failure, or right heart failure. "In vivo experiments demonstrated that lathyrol not only ameliorated BLM-induced pulmonary fibrosis in mice but also suppressed the reduction in PPARγ expression caused by pulmonary fibrosis." (PMID 41516261, 2025). "The inhibition of the TGF-β/Smad pathway via PPARγ activation mediates the suppression of fibroblast-to-myofibroblast transdifferentiation, which underlies the anti-pulmonary fibrosis effects of lathyrol." (PMID 41516261, 2025). "Myeloid-cell-specific PPARγ deficiency in mice led to increased severity of pulmonary fibrosis and increased lung collagen deposition after influenza A infection." (PMID 39451206, 2024). "From a therapeutic point of view this leads to a dilemma: Although NO deficiency increases PTHrP expression and thereby ADRP and PPARγ expression, the same trigger favours pulmonary fibrosis." (PMID 27581501, 2017). "Therefore, to investigate the detailed mechanism underlying lathyrol’s anti-pulmonary fibrosis effect, we also examined PPARγ expression in the lung tissues of mice with pulmonary fibrosis." (PMID 41516261, 2025). "Assuming that SARS-CoV/CoV-2 affects the pulmonary lipofibroblast transcriptional program that leads to pulmonary fibrosis, the use of peroxisome proliferator-activated receptor-gamma (PPARγ) agonists could be an option to reduce the risk of pulmonary fibrosis." (PMID 33195370, 2020). "In conclusion, Lathyrol inhibits myofibroblast transformation by suppressing TGF-β/Smad pathway activation through PPARγ activation, thereby exerting its anti-pulmonary fibrosis effects." (PMID 41516261, 2025). "During bleomycin-induced lung fibrosis, lipofibroblasts can transdifferentiate into activated myofibroblasts depending on PPARγ signaling and then revert to a lipofibroblast-like phenotype during the resolution phase." (PMID 41146597, 2025). "In vivo, lathyrol ameliorated pathological fibrosis in the lungs of mice with pulmonary fibrosis and this effect was blocked by a PPARγ inhibitor." (PMID 41516261, 2025). "Activation of PPARγ has also been shown to inhibit the TGF-β/Smad pathway which is a key pathway in pulmonary fibrosis." (PMID 41516261, 2025). "In vivo, PPARγ agonists such as lanifibranor and curcumin act by activating the PPARγ pathway to inhibit pulmonary fibrosis induced by bleomycin (BLM), SiO2, or paraquat." (PMID 41516261, 2025). "Studies have shown that M2-polarized alveolar macrophages exacerbate pulmonary fibrosis through PPARγ activation." (PMID 40017805, 2025). "This study confirms the anti-pulmonary fibrosis effects of lathyrol and elucidates the mechanism by which PPARγ activation mediates these effects." (PMID 41516261, 2025). "Taken together, these findings strongly suggest that PPARγ mediates the anti-pulmonary fibrosis effect of lathyrol in vivo." (PMID 41516261, 2025). "In summary, these findings indicate that lathyrol activates the PPARγ pathway, suggesting a potential mechanism for its anti-myofibroblast transforming and anti-pulmonary fibrosis effects." (PMID 41516261, 2025). "Although PPARγ activation has been demonstrated to suppress pulmonary fibrosis in vivo and in vitro, its detailed molecular mechanism remains poorly elucidated." (PMID 41516261, 2025). "In our study, we discovered that lathyrol exerts anti-pulmonary fibrosis effect by activating PPARγ." (PMID 41516261, 2025). "Consistent with this, GW9662 also counteracted the suppressive effect of lathyrol on the protein and mRNA expression levels of α-SMA, Col1α1, and PPARγ in mice with pulmonary fibrosis." (PMID 41516261, 2025).
pulmonary fibrosis (continued). "The hypermethylation of zinc finger protein 467 (ZNF467) gene downregulate its protein expression in pulmonary fibrosis, thereby decreasing the activation of peroxisome proliferator-activated receptor gamma (PPARγ)." (PMID 38915445, 2024). "Recent results showed that a PPARG agonist inhibited the expression of TGF-β1, fibronectin and collagen-I after restoring levels of PPARG in a lung fibrosis model induced by silica exposure in mice." (PMID 38576768, 2024). "Rosiglitazone treatment inhibited paraquat-induced pulmonary fibrosis in rats in a PPARγ-dependent manner, and the GW9662 antagonist blocked this antifibrotic effect." (PMID 39451206, 2024). "Our study demonstrates that asarinin can be used as a therapeutic agent for pulmonary fibrosis, and that PPARγ is its key target." (PMID 37679587, 2023). "In vivo, various PPARγ agonists, including troglitazone and rosiglitazone, were effective in inhibiting BLM-induced pulmonary fibrosis, and PPARγ agonists were also effective in inhibiting paraquat-induced pulmonary fibrosis." (PMID 37679587, 2023). "In vivo experiments revealed that asarinin promoted PPARγ expression, while attenuating bleomycin-induced pulmonary fibrosis." (PMID 37679587, 2023). "Overall, the activation of PPARγ negatively regulates the fibrosis process, suggesting that this receptor is a key target for pulmonary fibrosis treatment." (PMID 37679587, 2023). "PPARγ is vital to the development of pulmonary fibrosis, and its activation inhibits the development of various models of pulmonary fibrosis in vivo." (PMID 37679587, 2023). "Several studies have demonstrated the importance of PPARγ in preventing the development of pulmonary fibrosis." (PMID 37679587, 2023). "Intraperitoneal administration of asarinin to mice with pulmonary fibrosis showed that asarinin effectively attenuated pulmonary fibrosis, and this effect was significantly inhibited by the PPARγ inhibitor GW9662." (PMID 37679587, 2023). "In contrast, the protein and gene expression levels of PPARγ were significantly reduced in the lung tissue of BLM-induced pulmonary fibrosis mice compared with those in the control group and asarinin effectively inhibited this reduction." (PMID 37679587, 2023). "We have shown that metformin, as well as the PPARγ agonist rosiglitazone, accelerate the resolution of pulmonary fibrosis at least partly via inducing the transdifferentiation of collagen-secreting myofibroblasts into pro-alveologenic lipofibroblasts." (PMID 35741102, 2022). "Both pathways are induced by hypoxia, leading to decreased levels of PPARG and the subsequent differentiation of fibroblasts, leading to pulmonary fibrosis." (PMID 33807742, 2021). "Recently, the intersecting AOPs (AOP 347), including two MIEs, namely peroxisome proliferator-activated receptor-gamma (PPAR-γ) and toll-like receptor 4 (TLR4), associated with pulmonary fibrosis was proposed." (PMID 33809804, 2021). "In human lung, PPARγ agonists inhibit profibrotic phenotype fibroblasts and pulmonary fibrosis induced by bleomycin." (PMID 31131268, 2019). "We have recently demonstrated an interconversion between lipogenic and myogenic fibroblastic phenotypes in lung fibrosis, a process that is governed by TGFβ1 and PPARγ signaling pathways." (PMID 31278260, 2019). "In a bleomycin-induced model of lung fibrosis, PPARγ agonists induce an anti-fibrotic activity and RGZ attenuates fibrotic effects in rats." (PMID 31131268, 2019). "This review focused on recent studies that identified PPARγ as an important novel pathway with critical roles in regulating connective tissue homeostasis, with emphasis on skin and lung fibrosis and its role on systemic sclerosis." (PMID 26064084, 2015). "This review focused on recent studies that identified PPARγ as an important novel pathway with critical roles in regulating connective tissue homeostasis, with emphasis on skin and lung fibrosis and its role in systemic sclerosis." (PMID 26064084, 2015).
pulmonary fibrosis (continued). "Studies with animal models found that the PPARγ agonists troglitazone, pioglitazone, and rosiglitazone were able to inhibit lung fibrosis bleomycin induced." (PMID 26064084, 2015). "It’s reported that the deficiency of αCGRP may promote M2 macrophages polarization by activating the PPARγ signaling pathway, thereby exacerbating pulmonary fibrosis." (PMID 41383739, 2025). "Based on this, we also investigated whether lathyrol could activate PPARγ and whether its anti-pulmonary fibrosis and anti-myofibroblast transformation effects were also mediated by its interaction with PPARγ." (PMID 41516261, 2025). "The results showed that PPARγ expression was significantly downregulated in the lung tissues of mice with pulmonary fibrosis compared to the control group, while treatment of medium and high doses of lathyrol could inhibit this change." (PMID 41516261, 2025). "Therefore, exploring the detailed mechanism by which PPARγ activation suppresses pulmonary fibrosis is equally significant." (PMID 41516261, 2025). "In vivo, PPARγ inhibitor similarly attenuated the anti-pulmonary fibrosis effect of lathyrol." (PMID 41516261, 2025). "This suggests that anti-pulmonary fibrosis effect of lathyrol may be related to its influence on the PPARγ pathway." (PMID 41516261, 2025). "Although our study demonstrates that lathyrol exerts anti-pulmonary fibrosis and anti-myofibroblast transformation effects by activating PPARγ, it was not directly determined whether it functions as a direct ligand for PPARγ." (PMID 41516261, 2025). "Taken together, these findings suggest that BrMSCs and/or saroglitazar could inhibit BLM-activated TGF-β1/SMAD signaling pathway in pulmonary fibrosis with a remarkable role of PPARγ/α." (PMID 38376539, 2024). "Interestingly, inhibition of DNA methylase levels (DNMT1, DNMT3a, and DNMT3b) promotes PPARγ expression and improves pulmonary fibrosis." (PMID 37986543, 2024). "A recent study found that the peroxisome proliferator-activated receptor-γ (PPARγ) expression was low, but increased DNMT 1/DNMT3a and PPARγ promoter hypermethylation in IPF patients; therefore, the inhibition of DNA methylation that restored PPARγ led to attenuated pulmonary fibrosis." (PMID 37189665, 2023). "PPARγ is an important target for the prevention and treatment of pulmonary fibrosis." (PMID 37679587, 2023). "In our study, we demonstrated that asarinin inhibited the transition of various fibroblasts to myofibroblasts through the activation of PPARγ, which may be the mechanism by which it inhibits pulmonary fibrosis." (PMID 37679587, 2023). "Our study shows for the first time that asarinin exerts antifibrotic effects by activating PPARγ, providing evidence that asarinin may be useful for the treatment of clinical pulmonary fibrosis." (PMID 37679587, 2023). "Also, leptin signaling is necessary for bleomycin-induced lung fibrosis through a mechanism of peroxisome proliferator-activated receptor gamma (PPARγ) inhibition, which results in enhanced TGF-β1 signaling." (PMID 35610699, 2022). "Moreover, the PPARγ agonist rosiglitazone had a strong therapeutic effect on experimentally induced pulmonary fibrosis and inflammation." (PMID 35349484, 2022). "The beneficial effect of PPARγ activation in controlling lung fibrosis may be due to the receptor’s broad cellular distribution within the lung." (PMID 34529707, 2021). "In addition, the HDAC8 inhibitor NCC170 was shown to ameliorate idiopathic pulmonary fibrosis, in part, by increasing PPARγ expression." (PMID 31817161, 2019). "In this study on A549 cells, the PPARγ-dependent antifibrotic effects of sub-micromolar concentrations of RGZ are of particular interest in the context of excessive collagen production by myofibroblasts in lung fibrosis." (PMID 20178607, 2010). "However, the mechanism by which PPARγ activation suppresses myofibroblast transformation and inhibits pulmonary fibrosis remains unclear." (PMID 41516261, 2025).
pulmonary fibrosis (continued). "Besides, PPARG can beneficially and directly regulate the expression of antioxidant enzymes, contributing to decrease the excessive levels of ROS, molecules directly involved in the development of pulmonary fibrosis." (PMID 38576768, 2024). "Finally, we confirmed the co-expression of STAT6 and PPARγ in the pulmonary fibrosis tissues of BLM-treated and Calca+/− rats, as well as synchronization of the cytoplasmic and nuclear entry of PPARγ and STAT6, thus confirming that αCGRP deficiency promotes PPARγ nuclear translocation." (PMID 37231189, 2023). "Given that PPARγ also plays an important role in inhibiting the process of pulmonary fibrosis, whether the antifibrotic effect of bergenin mediated by Nrf2 is related to the activation of PPARγ in addition to the activation of the body’s antioxidant system remains to be further studied." (PMID 35204190, 2022). "Therefore, we conclude that the pulmonary PTHrP system seems more closely linked to ADRP and PPARγ rather than to inhibition of pulmonary fibrosis." (PMID 27581501, 2017). "Furthermore, consistent with the direct down-regulation of the associated factors peroxisome proliferator-activated receptor gamma (PPARγ), apolipoprotein E (APOE) and the apolipoprotein E receptor LRP8 by miR-130/301 in PH 9, both Pparγ and Lrp8 were decreased in pulmonary fibrosis." (PMID 26667495, 2015). "PPARγ serves as a gatekeeper of ECM and vascular cell homeostasis, playing beneficial roles in renal, cardiac, and pulmonary fibrosis." (PMID 41357323, 2025). "In this study, we first identified that lathyrol suppresses the fibroblast-to-myofibroblast differentiation by activating PPARγ to inhibit the TGF-β/Smad pathway, thereby alleviating BLM-induced pulmonary fibrosis in mice." (PMID 41516261, 2025). "Here, we observed for the first time that asarinin inhibited TGF-β1-induced myofibroblast transition by activating PPARγ, thereby attenuating BLM-induced pulmonary fibrosis." (PMID 37679587, 2023). "Numerous studies have demonstrated the potential role of PPARγ agonists and the inhibition of canonical WNT/TGF-β pathways in many pathologies leading to pulmonary fibrosis outside of BPD." (PMID 31131268, 2019). "A well-documented effect of PPARγ is to inhibit TGF-β expression and/or TGF-β signaling giving rise to an antifibrotic effect, which can be demonstrated in vivo in models of lung fibrosis for example." (PMID 19609456, 2009). "For example, metformin, an oral hypoglycemic drug, with strong properties as an antioxidant and anti-inflammatory molecule, attenuates lung fibrosis by inhibiting TGF-β1 signaling, modulating metabolic pathways, inducing lipogenic differentiation of fibroblasts and activating PPARG." (PMID 38576768, 2024). "By activating PPARγ, asarinin inhibits the TGF-β canonical Smad pathway and the non-canonical AKT and MAPK pathways, thereby inhibiting the transition of fibroblasts to myofibroblasts, and thus lung fibrosis." (PMID 37679587, 2023). "The fact that PPARγ can inhibit fibroblast activation/differentiation and pulmonary fibrosis suggests that KLF4 induction may be a conserved antifibrotic brake that mediates some of the antifibrotic actions of both cAMP-dependent and PPARγ-dependent agonists." (PMID 35852857, 2022). "We previously demonstrated that a PPARγ antagonist (GW9662) can reverse the enhanced efferocytosis, reduced pro-inflammatory cytokine expression, and neutrophil recruitment into the lung following apoptotic cell instillation in lung fibrosis." (PMID 35327639, 2022).
pulmonary fibrosis (continued). "Intriguingly, this pattern inversely correlated with WAT PPARγ and C/EBPα, while there was a positive correlation with hydroxyproline and type I collagen levels, in agreement with the previously proposed role of PGF (2alpha) signaling in pulmonary fibrosis." (PMID 29656108, 2018). "Suggestions that leptin could play a key role in lung fibrosis include that it augments TGF-β1 signaling in lung fibroblasts; it does so by inhibiting PPARγ." (PMID 27642238, 2016). "Furthermore, a study on a murine model of pulmonary fibrosis has recently been conducted to evaluate the safety and efficacy of an original PPARγ modulator called GED-0507-34-Levo (GED-0507), in halting or even reversing pulmonary fibrosis induced by bleomycin." (PMID 33409282, 2020).